CSDE1 (cold shock domain containing E1)
Diseases named in the same sentence as CSDE1 in open-access papers (continued):
Sharing a sentence is not in itself a finding about the gene and the disease.
Alpha-thalassemia (2 papers, 2018 to 2024). Alpha-thalassemia is an inherited hemoglobinopathy characterized by impaired synthesis of alpha-globin chains leading to a variable clinical picture depending on the number of affected alleles. "Molecular assessment of tumor tissue suggests somatic pathogenic variants in the genes mastermind like transcriptional coactivator 3 (MAML3), alpha thalassemia/mental retardation syndrome X (ATRX), and cold shock domain-containing E1 (CSDE1) are also associated with metastatic behavior." (PMID 38799767, 2024).
Diamond-Blackfan anaemia (2 papers, 2018 to 2020). "With recent research advances, CSDE1 has been found to play an important role in other diseases, including Diamond-Blackfan anaemia (DBA), autism spectrum disorders (ASDs) and embryonic lethality." (PMID 31987048, 2020).
pancreatic cancer (2 papers, 2017 to 2019). "To date, the role of UNR/CSDE1 has been studied in melanoma, breast, prostate, and pancreatic cancer." (PMID 31027221, 2019). "The mRNA expression profile of 186 pancreatic cancer patients from the TGCA dataset was correlated with the expression of CSDE1 using Spearman and Pearson tests." (PMID 28763470, 2017). "Based on these findings, we propose UNR/CSDE1 as an independent prognostic biomarker for resectable pancreatic cancer." (PMID 28763470, 2017).
prostate carcinoma (2 papers, 2024 to 2026). A carcinoma that arises from epithelial cells of the prostate gland. "The protease hepsin binds to CSDE1 IRES and inhibits its activity, resulting in reduced CSDE1 translation in prostate cancer cells." (PMID 38600987, 2024).
squamous cell carcinoma (2 papers, 2024). A carcinoma arising from squamous epithelial cells. "CSDE1 also behaves as a tumor suppressor in squamous cell carcinoma, where it promotes oncogene-induced senescence by repressing the synthesis of YBX1 and enhancing the stability of mRNAs encoding senescence-associated secretory phenotype (SASP) factors." (PMID 38600987, 2024).
thyroid cancer (2 papers, 2020 to 2022). "A recent study has reported that miR-132 and miR-212 cluster function as a tumor suppressor in thyroid cancer cells by CSDE1 mediated post-transcriptional program." (PMID 32319512, 2020). "miR-212 and miR-132 cluster can hinder thyroid cancer progression by directly targeting CSDE1." (PMID 35923244, 2022).
triple-negative breast carcinoma (2 papers, 2022 to 2025). An invasive breast carcinoma which is negative for expression of estrogen receptor (ER), progesterone receptor (PR), and human epidermal growth factor receptor 2 (HER2). "In triple-negative breast cancer, decreased expression of miR-371b-5p drives tumor progression through CSDE1/RAC1 regulation." (PMID 40302797, 2025).
Anxiety (1 paper, 2019). Intense feelings of nervousness, tension, or panic often arise in response to interpersonal stresses. "In addition, seizures, macrocephaly, anxiety, ADHD, hypotonia, and ocular defects were also associated with CSDE1 LGD variants." (PMID 31579823, 2019).
B-cell lymphomas (1 paper, 2013). "Three out of 13 murine B-cell lymphomas induced by the leukemogenic Akv1-99 virus had retroviral integrations into the Nras/Csde1 locus." (PMID 23418499, 2013).
colon cancer (1 paper, 2019). "We firstly evaluated UNR/CSDE1 expression in human colon cancer derived cell lines and patient samples." (PMID 31027221, 2019).
cutaneous melanoma (1 paper, 2024). A primary melanoma arising from atypical melanocytes in the skin. "However, the CSDE1 cytoplasmic/nuclear ratio exhibited a positive correlation with adverse clinical features of primary tumors and emerged as a robust indicator of progression free survival in cutaneous melanoma, highlighting the potential of CSDE1 as a biomarker of prognosis." (PMID 38396995, 2024). "Importantly, patients with metastasis naïve for treatment derived from primary cutaneous melanoma showed a significant correlation between high C/N CSDE1 ratios and worse progression free survival (PFS), increasing the risk of PFS by 6.6 times (means of 1.8 years for low vs 0.3 years for high C/N)." (PMID 38396995, 2024).
glioblastoma (1 paper, 2024). The most malignant astrocytic tumor (WHO grade IV). "Of note, a recent study revealed the antibiotic clofoctol as a drug targeting CSDE1 for the treatment of glioblastoma, placing CSDE1 in the cancer druggable space." (PMID 38396995, 2024).
Hypercholesterolemia (1 paper, 2023). An increased concentration of cholesterol in the blood.
lymph node metastasis (1 paper, 2022). "In addition, Kaplan–Meier analysis of the overall survival of patients with high CSDE1 expression showed poor prognosis with lymph node metastasis." (PMID 35490208, 2022).
mental retardation syndrome X-linked (1 paper, 2021). "The ‘Wnt-signal’ type involves somatic mutations in cold shock domain containing E1 (CSDE1), thalassemia/mental retardation syndrome X-linked (ATRX) and mastermind-like transcriptional coactivator (MAML3)." (PMID 34201922, 2021).
neurodevelopmental disabilities (1 paper, 2021). "We identified de novo exonic insertions in genes with a high probability of LoF intolerance or haploinsufficiency (pLI ≥ 0.9) only in affected individuals, including an exonic insertion in CSDE1, a gene recently implicated in patients with ASD and neurodevelopmental disabilities." (PMID 34838103, 2021).
nodular melanoma (1 paper, 2024). "We observed that CSDE1 expression was modestly but significantly lower in samples with Breslow >1mm and in nodular melanoma." (PMID 38396995, 2024).
oligodendroglioma (1 paper, 2024). A well-differentiated (WHO grade II), diffusely infiltrating neuroglial tumor, typically located in the cerebral hemispheres. "Both these blocks are negatively correlated with the group of genes GPBP1L1, LRRC41, CSDE1, FBXO42, and SFRS4, which are associated with the oligodendroglioma type." (PMID 38812741, 2024).
parasitemia (1 paper, 2024). "Three modules led by the hub genes RIOK3, CSDE1, and SEC62 negatively associated with protection and positively associated with both prevaccination anti–CSP IgG and parasitemia at first vaccination." (PMID 38687615, 2024).
prostate tumor (1 paper, 2020). "When splenocytes from these mice were cocultured with either parental B16 or TC2 prostate tumor cells expressing either CSDE1 or CSDE1* epitopes, only mice vaccinated with B16-CSDE1* and treated with ICB showed an IFNγ recall response against parental B16 cells (p < 0.01 one-way ANOVA)." (PMID 32034147, 2020).
thyroid tumor (1 paper, 2021). A benign or malignant neoplasm affecting the thyroid gland. "It has been observed that CSDE1 reduced thyroid tumor cell proliferation." (PMID 34419060, 2021).
tumor (21 papers, 2018 to 2025). "An initial VSV-IFNβ variant drove tumor escape via a predictable CSDE1 (Cold Shock Domain-containing E1) mutation (CSDE1P5S) that enabled tumors to evade oncolytic virotherapy." (PMID 41294689, 2025). "CSDE1 is a tumor suppressor gene that encodes the CSDE1 factor, which is involved in development, messenger RNA stability, internal initiation of translation, cell-type-specificapoptosis, and neuronal differentiation." (PMID 36699028, 2022). "CSDE1-mutated tumours exhibited a CSDE1 DNA copy number deletion and inadequate CSDE1 mRNA expression, which supported its role as a tumour suppressor in tumourigenesis." (PMID 31987048, 2020). "These prognostic values indicated that high expression of CSDE1 was strongly associated with tumor progression and might be related to metastatic probability in TNBC." (PMID 35490208, 2022). "Using the tumor-bearing mice model with Csde1 knockout, we demonstrated that Csde1 deletion significantly inhibited tumor growth." (PMID 41353256, 2025). "Single-cell RNA sequencing revealed that Csde1 knockout reshaped the tumor immune microenvironment, particularly by significantly increasing TIL-B levels, a finding confirmed by flow cytometry and immunofluorescence." (PMID 41353256, 2025). "Clofoctol binds to CSDE1 and enhances its association with KLF13 mRNA -encoding a tumor suppressor- leading to KLF13 mRNA stabilization, reduction of tumor growth and increased mouse survival." (PMID 38600987, 2024). "Images were quantified digitally as detailed in Materials and Methods, and CSDE1 levels were correlated with tumor parameters." (PMID 38396995, 2024). "In this regard, recent studies have found that differences in epigenetic modification of the RNA-binding protein cold shock domain-containing protein E1 (CSDE1) can lead to high or low immunogenic heterogeneity in early neonatal tumor cells." (PMID 38816871, 2024). "We discuss context-specific functions of CSDE1 in tumor development, its mechanisms of action, and highlight features that support its role as a molecular adaptor." (PMID 38600987, 2024). "The molecular mechanisms that CSDE1 employs to promote tumor formation in these cancer types remain largely elusive." (PMID 38600987, 2024). "The Wnt Signalling cluster, distinguished by mutations in cold shock domain-containing protein E1 (CSDE1) and somatic gene fusions of mastermind-like transcriptional coactivator 3 (MAML3), is crucial in shaping PPGLs’ tumor features." (PMID 38745767, 2024). "Cytoplasmic functions of CSDE1 are important for tumor promotion, including the regulation of the synthesis of EMT factors resulting in increased invasiveness or the modulation of TCPTP mRNA stability leading to immune escape." (PMID 38396995, 2024). "Collectively, we showed that dysregulated miR-371b-5p/CSDE1/RAC1 axis deepens tumor progression and aggressiveness in patients with TNBC and suggested that miR-371b-5p is a potential prognostic biomarker for TNBC." (PMID 35490208, 2022). "CSDE1 is ranked by NDSI as the strongest CNA-based tumour suppressor and 5th strongest driver averaged across all classes." (PMID 35975235, 2022). "To explore the mechanism underlying CSDE1-related tumor progression in TNBC, we verified that Rac1 expression was regulated by CSDE1 in TNBC." (PMID 35490208, 2022). "We found that LINC01234 had tumor-promoting effects in BC by attenuating the suppression of miR-525-5p on CSDE1." (PMID 35923244, 2022). "Cold shock domain containing E1 (CSDE1) is an RNA binding protein (RBP) that is involved in tumor progression." (PMID 34419060, 2021). "CSDE1 was also overexpressed by an average of almost 3-fold in tumour samples compared with their adjacent normal tissues in CRC patients." (PMID 31987048, 2020). "It was previously reported that some key translation regulation factors played an important role in affecting platinum sensitization, and CSDE1 was found to be involved in regulating platinum sensitization of tumours." (PMID 31987048, 2020).
tumor (continued). "The bidirectional role of CSDE1 in translation reprogramming contributes to its bidirectional role in cancers: CSDE1 can act as both an oncogene and a tumour suppressor in different tumours." (PMID 31987048, 2020). "Here, we observed that metastatic tumor samples presented higher expression levels of CSDE1 than stages II or III." (PMID 31027221, 2019). "Samples were then grouped according to their tumor and untransformed origin, and statistical analysis revealed a significant upregulation of CSDE1 mRNA in tumor samples compared to their untransformed samples (p = 0.0004)." (PMID 31027221, 2019). "Notably, depleting B cells in Csde1 knockout mice reversed the inhibitory effect of Csde1 deletion on tumor progression, underscoring the critical role of B cells in this process." (PMID 41353256, 2025). "CSDE1 has been involved in other tumor types, often displaying context-specific functions." (PMID 38396995, 2024). "Nevertheless, in most examples studied to date CSDE1 performs tumor promoting roles." (PMID 38600987, 2024). "Only the CSDE1 gene mutation, (c.*2010T>AT), was a 3'-UTR variant detected in this tumor." (PMID 37273678, 2023). "Our data demonstrate that miR-371b-5p is a tumor-suppressive miRNA that regulates the CSDE1/Rac1 axis and could be a potential prognostic biomarker for TNBC." (PMID 35490208, 2022). "Furthermore, we analyzed CSED1 protein expression in BC and the tumor-adjacent normal tissues using IHC and found that CSDE1 levels were significantly increased in BC than in normal tissues, and its levels were positively correlated with LINC01234 expression." (PMID 35923244, 2022). "In addition, miR-371b-overexpressing xenograft tumors showed decreased expression of CSDE1 and Rac1 compared to the miR-con tumor." (PMID 35490208, 2022). "Besides, CSDE1 has been recorded to facilitate tumor progression by driving a posttranscriptional program." (PMID 35923244, 2022). "Interestingly, we found CSDE1 mRNA upregulation in 9/10 tumor samples compared to their untransformed samples." (PMID 31027221, 2019). "However, the role of UNR/CSDE1 as a prognosis biomarker appears to be different depending on the type tumor." (PMID 31027221, 2019). "Interestingly, the intracellular distribution of CSDE1 changes with tumor stage." (PMID 38396995, 2024). "Interestingly, we found that CSDE1 at upregulated levels could act as an oncogene to regulate tumor cell growth, migration, and invasion by modulating the transcription of RAC1, a well-known proto-oncogene." (PMID 35490208, 2022). "However, CSDE1 plays an opposing role in some other types of tumours." (PMID 31987048, 2020). "ATRX, CSDE1 and NF2 become the top SNA-based, CNA-based and mixed tumour suppressors, respectively." (PMID 35975235, 2022).
cancer (17 papers, 2013 to 2025). A tumor composed of atypical neoplastic, often pleomorphic cells that invade other tissues. "In fact, one of our top hits is CSDE1, an RNA-binding protein implicated in multiple diseases including several types of cancer." (PMID 39972349, 2025). "Over the years, CSDE1 has been identified within gene signatures linked to various cancer types, and more recently it has been proposed as a potential biomarker of prognosis and response to treatment." (PMID 38600987, 2024). "As high CSDE1 expression was associated with poor prognosis in lymph node-positive patients, we investigated the contribution of CSDE1 in cancer cell migration and metastasis in TNBC." (PMID 35490208, 2022). "CSDE1 has been implicated in various cancers and immune responses." (PMID 41353256, 2025). "Given the context-specific functions of CSDE1 in cancer and our poor understanding of its roles in healthy cells, however, it is crucial to expand our knowledge before considering CSDE1 for therapeutic applications." (PMID 38600987, 2024). "Unfortunately, no unbiased efforts have been reported to identify partners of mammalian CSDE1 in cancer cells, a gap that must be addressed to fully understand CSDE1 binding and regulation of mRNA targets." (PMID 38600987, 2024). "Since then, research on CSDE1 has rapidly grown, revealing context-specific roles of this protein in cancer." (PMID 38600987, 2024). "This review focuses on one such modulator, the protein CSDE1, and its pivotal role in regulating cancer hallmarks." (PMID 38600987, 2024). "In summary, CSDE1 regulates five of the fourteen cancer hallmarks described by Hanahan, namely proliferation, survival, invasion, senescence and immune evasion, via regulation of specific mRNA targets." (PMID 38600987, 2024). "We first summarize the literature linking CSDE1 with cancer development and highlight cancer hallmarks regulated by CSDE1." (PMID 38600987, 2024). "A potential link of CSDE1 with cancer dates back to 1997, when evidence of transcriptional interference between UNR and the N-Ras locus was reported." (PMID 38600987, 2024). "CSDE1 is emerging as an important regulator of cancer cell behavior, and as a flexible molecular adaptor." (PMID 38600987, 2024). "The core set of commonly bound transcripts were enriched in functional terms related to stress response, cell migration and (post)-transcriptional regulation, underscoring the relevance of CSDE1 as a modulator of cancer cell behavior." (PMID 38600987, 2024). "After examining the pulled‐down proteins by lncRNA ARHGAP5‐AS1 using mass spectrometry proteomics, we identified multiple cancer‐related proteins including CSDE1, ZC3HAV1, CCT8, CKAP4, PARP1, PEG10 and APEX1 in HepG2." (PMID 36354136, 2022). "Multiple lines of evidence demonstrated that the RNA‐binding protein CSDE1 acts as an oncogene in cancers and regulates the translation and stability of mRNAs at the post‐transcriptional level." (PMID 36354136, 2022). "CSDE1 has been shown to be a potential drug target, prognostic biomarker and anticancer drug sensitizer for various cancers." (PMID 31987048, 2020). "CSDE1, which has already been validated to be involved in several cancers, was predicted as a possible candidate mRNA to interact with FUS through bioinformatics in present work." (PMID 32808651, 2020). "In human colorectal cancer (CRC), CSDE1 promoted cancer cell survival, invasion, and resistance to apoptosis." (PMID 31987048, 2020). "Moreover, we validated CSDE1 as a neosubstrate of CRBN, an mRNA and stress-granule associated protein that has been linked to different types of cancer." (PMID 39972349, 2025). "CSDE1 is primarily localized in the cytoplasm of cancer cells." (PMID 38600987, 2024). "Based on the analysis of the prognostic value of CSDE1, we suggested that high expression of CSDE1 could affect cancer cell progression in TNBC." (PMID 35490208, 2022).
cancer (continued). "To elucidate whether CSDE1 regulates cancer malignancy by regulating Rac1 expression, we rescued Rac1 expression in CSDE1-knockdown cells." (PMID 35490208, 2022). "Based on ribopuromycylation method analysis, more than 80% of CSDE1-NRs were puromycin positive, which could be directly visualized through localized translation in the cancer cell line BeWo." (PMID 31987048, 2020). "Cancers are the most widely and thoroughly investigated diseases related to CSDE1." (PMID 31987048, 2020). "In cancer, CSDE1 has been shown to regulate c-Fos, c-Myc, Pten, Rac1, or Vimentin." (PMID 31027221, 2019). "Since colonspheres are an appropriate 3D in vitro cancer model and have formerly demonstrated their association with tumor cell undifferentiated phenotype and aggressiveness, we decided to evaluate UNR/CSDE1 expression in different origin CRC derived cell lines." (PMID 31027221, 2019). "First, cancer cell viability and Ki67-positive cells were significantly impaired in MDA-MB-231 cells treated with CSDE1 siRNAs." (PMID 35490208, 2022). "High-throughput studies performed in erythroblasts suggest that STRAP can affect the expression of select CSDE1 targets without significantly altering CSDE1 RNA-binding capability, but equivalent studies in cancer cells are missing." (PMID 38600987, 2024). "Likewise, CSDE1 acts as a proto-oncogene by regulating c-myc, c-fos, RAC1, and vimentin expression and promotes metastasis and invasion in cancer." (PMID 35490208, 2022). "In addition, we found in this list established cancer genes involved in other types of cancer, such as PDE4DIP, SF3B1, AHNAK, COPB2, CSDE1, KIF5B, NDUFA10, RSRC2." (PMID 31949199, 2020).